SIRPA (signal regulatory protein alpha)
Diseases named in the same sentence as SIRPA in open-access papers (continued):
Sharing a sentence is not in itself a finding about the gene and the disease.
glioblastoma (continued). "Therefore, accumulating evidences indicate that inducing M1-like TAMs polarization and targeting the CD47/SIRPα axis could uncover the clinical translational potential for glioblastoma treatment." (PMID 35410993, 2022). "In the present manuscript, we describe the generation and characterization of nanobodies against SIRPα, as targeting agents for SIRPα-positive glioblastoma (GBM)-infiltrating myeloid cells." (PMID 34917090, 2021). "GSC-derived exosomes induced SIRPA expression in macrophages and suppressed their phagocytic ability, thereby enhancing proliferation, migration, invasion and EMT of glioblastoma cells." (PMID 42116089, 2026). "In contrast, critical biomarkers for glioblastoma, including CD47 and SIRPα, exhibited higher expression among these immune checkpoints, which are correlated with a CRG low-risk signature and improved prognosis." (PMID 38956740, 2024). "Genetic deletion or antibody blockade of SIRPα, CD22, CD33 and PD1 enhance the microglial phagocytic activities against Aβ and glioblastoma, making the receptors attractive therapeutic targets for treating AD and brain tumor." (PMID 37483607, 2023). "Late-breaking studies reported that targeting CD47 by SIRPα-based fusion protein increased macrophage-mediated elimination of NSCLC and glioblastoma cells." (PMID 31829270, 2019). "The expression of CD47 is rare, suggesting that the CD47 and SIRPα protein interaction is not typical in newly diagnosed glioblastoma." (PMID 38786045, 2024). "The augmentation of macrophage phagocytosis of tumor cells has been observed in various preclinical tumor models, such as small-cell lung cancer, anaplastic thyroid carcinoma, and glioblastoma, through the implementation of monoclonal antibodies or fusion proteins to obstruct the CD47/SIRPα axis." (PMID 38532108, 2024). "Bioinformatic analyses of scRNA seq datasets of eighteen glioma patients (two with low-grade glioma, eleven with newly diagnosed glioblastoma, and five with recurrent glioblastoma) demonstrate that SIRPA is expressed in myeloid cells, and multiplex imaging shows P2RY12+ microglia also express SIRPα." (PMID 38786045, 2024). "The increased expression of SIRPα in macrophages could subsequently result in enhanced STAT1 phosphorylation and positively affect M1 macrophages polarization, the induced M1 macrophages contribute to the phagocytosis of glioblastoma cells." (PMID 35410993, 2022). "The co-culture of apoptotic LN-229 increased the CD40+ GFP+ cell population to ~10% in the parental, SIRPα-negative and MERTK-negative cells, showing that microglial phagocytosis was more efficient on apoptotic glioblastoma cells." (PMID 37483607, 2023).
glioma (25 papers, 2016 to 2025). A benign or malignant brain and spinal cord tumor that arises from glial cells (astrocytes, oligodendrocytes, ependymal cells). "In general, gliomas had lower transcript expression of SIRPA (gene encoding SIRPalpha) and higher of PD-L1 (CD274), PD-L2 (PDCD1LG2), TIM-3 (HAVCR2), PD-1 (PDCD1) (respectively)." (PMID 36768201, 2023). "Of note, CD47, which is known to be upregulated in glioma stem cells, binds to SIRPα on the surface of macrophages to exert a “don't eat me” signal, thus contributing to immune evasion of the tumor cells by preventing phagocytosis by macrophages." (PMID 37791581, 2023). "Further, dropping the expression level of CD47 and SIRPα on glioma cells and macrophages resulted from the combination treatment suggests the deteriorating anti-phagocytic ability of glioma." (PMID 34671362, 2021). "CD47 is a transmembrane protein overexpressed in glioma cells that binds to the receptor SIRPA on the surface of monocytes/macrophages and MG cells inhibiting phagocytic functions and allowing tumors to escape the innate immune surveillance." (PMID 34168976, 2021). "However, comprehensive studies are warranted to ascertain the clinical effectiveness of SIRPα blockade, either as a standalone therapy or in conjunction with other immunotherapies in glioma." (PMID 38342925, 2024). "Furthermore, the CD47/SIRPα axis expression in the mouse glioma model was consistent with that in clinical patients." (PMID 39713206, 2024). "Using mouse glioma models which enable the differentiation of genetically labelled MDM (Ccr2 RFP) and MG (Cx3cr1 GFP), they showed that microglia associated tumor cells increase tumor cell phagocytosis in response to CD47/SIRPA axis inhibition." (PMID 34168976, 2021). "Indeed, the resident MG is capable of phagocytosis when meeting with glioma cells in response to myeloid checkpoint CD47- Signal regulatory proteinα (SIRPα) blockade in vivo." (PMID 34671362, 2021). "In this review, we examined the role of phagocytic cell death in gliomas and strategies to modulate the balance between “don’t-eat-me” CD47/SIRPα and “eat-me” CALR/STC1 axes for therapeutic benefits." (PMID 38786045, 2024). "In the analysis of CD47/SIRPα as a function of WHO grade, SIRPα expression is significantly reduced in grade 4 gliomas." (PMID 38786045, 2024). "mIAP301, an anti-CD47 mAb that blocks the binding between murine CD47 and SIRPα, has been shown to enhance phagocytosis of GL261 glioma cells and glioma stem cells by macrophages and prolonged mouse survival." (PMID 38786045, 2024). "Owing to the specific role of QPCTL in the binding between CD47 and SIRPα, targeting QPCTL instead of targeting CD47 in gliomas overcomes the side effects of targeting CD47." (PMID 37063864, 2023). "SIRPα-Fc blocks CD47-SIRPα impressively, also triggering autophagy of glioma cells thus promoting survival in GBM models, and the prognosis is better with chloroquine." (PMID 35135556, 2022). "Over the course of glioma-macrophage co-culture experiments, we found interesting results with CD47 and SIRPα expression." (PMID 32020472, 2020). "Glioma cells are known to upregulate the expression of the surface protein CD47, which acts as a ‘do not eat me’ signal, inhibiting phagocytosis by binding to its receptor SIRPα on MDM and MG." (PMID 40845580, 2025). "Despite the progress made with SIRPα in cancer research, its benefits have not yet been applied to the field of glioma." (PMID 38342925, 2024). "Another research found the CD47/SIRPα axis as a “do not eat me signal” of glioma and blocking CD47 effectively restraining the glioma progression." (PMID 37849438, 2023). "However, in glioma, the phagocytosis of GAMs is greatly reduced, due to the high expression of CD47 along with signal regulatory protein alpha (SIRPa) on the surface of GAMs." (PMID 36969167, 2023).
glioma (continued). "Correlation analysis showed that ZBTB42 was positively related to PD1, PD-L1, PD-L2, CTLA4, TIM3, and LAG3 in LGG and positively related to PD-L1, PD-L2, SIRPA in GBM, suggesting that the high expression of ZBTB42 may promote glioma progression via immune suppression microenvironment." (PMID 36762114, 2023). "However, unexpectedly, the levels of PD1, SIRPα, and certain integrins were increased, implying that the utilization of Vorinostat along with PD1 or other targeted drugs may be beneficial in the treatment of glioma." (PMID 40548122, 2025). "Glioma cells express high levels of CD47, which binds signal regulatory protein alpha of microglia, to release a “do not eat me” signal and suppress phagocytosis of microglia." (PMID 37462801, 2023).
atherosclerosis (20 papers, 2008 to 2026). A disease characterized by the build-up of fatty material and calcium deposition in the arterial wall resulting in partial or complete occlusion of the arterial lumen. "This study suggests that dysregulated communication between CD47 and SIRPα may also underlie the progression of atherosclerosis in humans." (PMID 39736852, 2025). "Systemic blockade of CD47 with antibodies against its receptor SIRPα reduced plaque vulnerability and lesion size in atherosclerosis models." (PMID 41546123, 2026). "The upregulation of the CD47: SIRPa axis inhibits the clearance of apoptotic cells within plaque lesions, hastening the advancement of atherosclerosis." (PMID 39736852, 2025). "Blockade of the CD47/SIRPa interaction is a novel strategy for the treatment of atherosclerosis, cancer and autoimmune diseases." (PMID 41184328, 2025). "CD47−/−/ApoE−/− mice are protected from atherosclerosis, and systemic inhibition of SIRPα -mediated signaling appears more effective in reducing the necrotic core area in murine atherosclerosis models compared to global CD47 inhibition." (PMID 39926714, 2024). "Another example of an approach to restoring efferocytosis is by disrupting “don’t-eat-me” signaling using anti-CD47 or anti-SIRPα monoclonal antibodies to drive resolution and mitigate atherosclerosis." (PMID 36710920, 2023). "The CD47: SIRPα axis act as a don’t eat me signal and up-regulation of this pathway prevents clearance of apoptotic cells within plaque lesions, accelerating atherosclerosis progression." (PMID 33483751, 2021). "In order to further establish the potential pathological/clinical relevance of the regulation of natural IgM antibody production by SIRPα in vivo, we decided to explore the role of SIRPα in atherosclerosis." (PMID 33162986, 2020). "Collectively, our data identify SIRPα as a unique B1 cell inhibitory receptor acting to control B1 cell migration, and imply SIRPα as a potential therapeutic target in atherosclerosis." (PMID 33162986, 2020). "This identifies SIRPα as a novel immunoinhibitory receptor on B1 cells with unique regulatory functions and potential for therapeutic targeting in atherosclerosis." (PMID 33162986, 2020). "As natural antibodies are atheroprotective, we investigated the involvement of SIRPα signaling in atherosclerosis development." (PMID 33162986, 2020). "As macrophages are important players in development of atherosclerosis we cannot exclude their contribution to the observed phenotype, especially since the SIRPα counter-receptor CD47 appears involved in pathogenesis of atherosclerosis through inhibition, e.g., macrophage efferocytosis." (PMID 33162986, 2020). "Our findings also imply SIRPα as a potential therapeutic target in atherosclerosis." (PMID 33162986, 2020). "Moreover, direct blockade of SIRPα itself has also been shown to reduce atherosclerosis." (PMID 41546123, 2026). "CD47 antibody B6H12 downregulates VEGFR2 and SHP-2 phosphorylation and CD47 binds SIRPα and TSP-1 to regulate the expression of VEGF and VEGFR2, thereby affecting the progression of atherosclerosis." (PMID 32733941, 2020). "SIRPα negatively regulates β2 integrin-mediated monocyte adhesion, transendothelial migration and phagocytosis, thus may serve as a critical molecule in preventing excessive activation and accumulation of monocytes in the arterial wall during early stage of atherosclerosis." (PMID 18820737, 2008). "Mice lacking the cytoplasmic tail of SIRPα (SIRPαΔCYT mice) in their hematopoietic compartment are protected against atherosclerosis with increased natural antibody levels against oxidized lipids." (PMID 33162986, 2020).
colon carcinoma (19 papers, 2018 to 2025). "Studies have found that using blocking antibodies targeting CD47 overexpressed on colon cancer cells and SIRPα on TAMs can inhibit the migration of colon cancer cells." (PMID 40873588, 2025). "To investigate anti‐SIRPα mAb therapy‐induced inhibitory effects on sporadic colon cancer growth, we used a CDX2P9.5‐NLS Cre;APC+/FLOX (CPC‐APC) mouse model." (PMID 30460349, 2018). "Interestingly, under hypoxic conditions, TAMs showed decreased SIRPα expression accompanied by increased phagocytic activity, whereas colon cancer cells showed elevated expression of CD47 and exhibited greater invasiveness." (PMID 40873588, 2025). "Moreover, PEG2000‐SiNcTI‐Ph/CpG‐ZIF‐8@CM evades immune surveillance to target CT26 colon tumors in mice mediated by CD47/signal regulatory proteins α (SIRPα) interaction and PD‐1/programmed death ligand 1 (PD‐L1) interaction, respectively." (PMID 38728587, 2024). "This suggests that targeting the CD47/SIRPα axis may be a potential therapeutic strategy for colon cancer immunotherapy." (PMID 37465677, 2023). "Anti-SIRPα antibody treatment leads to enhanced macrophage phagocytic activity and reduced tumor progression in a mouse model of colon cancer and CD47-SIRPα signaling promotes the expansion and metastasis of colon cancer cells in tumor microenvironments that are rich in tumor-associated macrophages." (PMID 32082311, 2020). "For the first time, we described that, in colon cancer, hypoxia impacts the SIRPα/CD47 axis through the decrease of macrophage SIRPα expression, which may favor their phagocytic capacity." (PMID 32231135, 2020). "In vivo, NILK-2401 significantly delayed tumor growth in a NOD-SCID colon cancer model and a syngeneic mouse model using human CD47/human SIRPα transgenic mice and prolonged survival." (PMID 38720892, 2024). "When evaluated using TCGA and GTEx datasets, we observed that CD47 expression was markedly higher in colon cancer contrasted with healthy counterparts, while SIRPα expression was not different." (PMID 37291116, 2023). "In non-neoplastic colonic mucosae as well as colon cancer stroma, TAIs positive for SIRPA, CD68, or CD163 were variably observed." (PMID 33799989, 2021). "Thus, we evaluated SIRPα and CD47 expression in human colon cancer." (PMID 37291116, 2023).
leukemia (17 papers, 2013 to 2025). A malignant (clonal) hematologic disorder, involving hematopoietic stem cells and characterized by the presence of primitive or atypical myeloid or lymphoid cells in the bone marrow and the blood. "Targeting the CD47/SIRPα, Hu5F9-G4 antibody has been used in combination with Azacitidine, and the results have shown promising effects in leukemia stem cells (NCT03248479)." (PMID 35395787, 2022). "In a pilot experiment, T cells modified with one of the SIRPα-based CARs showed dose dependent leukemia cell control." (PMID 39086976, 2022). "Through the transcriptional repression of Signal-Regularity Protein α (SIRPα), p21 promotes leukemia cell phagocytosis and, subsequently, the pro-inflammatory reprogramming of phagocytic macrophages that extends to surrounding macrophages through Interferon γ." (PMID 36347876, 2022). "Alternatively, TAMs induce the overexpression of CD47 ligand on pancreatic CSCs, HCC CSCs, and leukemia stem cells, which bind to signal-regulatory protein α (SIRPα) on phagocyte cells and thus protect them from cell-mediated phagocytosis." (PMID 35395787, 2022). "SIRPα/CD123 BsAb also established its safety by demonstrating low CD47-related on-target off-leukemia toxicity." (PMID 35978372, 2022). "Our findings provide direct genetic and functional evidence that macrophage-expressed p21 is a key regulator of leukemia cell phagocytosis, acting by repressing the transcription of the phagocytosis inhibitory receptor SIRPα." (PMID 36347876, 2022). "In this study, we observed that SIRPα overexpression in BMDMs decreased phagocytosis of L1210 leukemia cells, while SIRPα knockdown in BMDMs and CD47 knockdown in L1210 cells both increased phagocytosis by macrophages." (PMID 30105024, 2018). "Accordingly, TAMs promote the upregulation of cluster of differentiation 47 (CD47) ligand on different cancers stem cells (including pancreatic, HCC and leukemia), which interacts to signal-regulatory protein alpha (SIRPA) on immune cells inhibiting phagocytic process." (PMID 39981232, 2025). "To overcome these limitations, we here validated a soluble extracellular domain of mouse SIRPα (36 KD) and confirmed that mSIRPαext could not only promote M1 polarization but also increase phagocytosis of L1210 leukemia cells by macrophages." (PMID 30105024, 2018). "Thus, CD47 expression on leukemia cells and SIRPα expression on LAMs were investigated." (PMID 40881683, 2025). "SIRPα-αCD123 fusion antibodies disrupted CD47/SIRPα signalling in AML cell lines and specifically enhanced leukemia stem cell clearance." (PMID 39697225, 2024). "DSP107 also blocked the cross talk of SIRPα with CD47 and triggered phagocytosis in several lymphomas, leukemia, and carcinoma cell lines in vitro." (PMID 35978372, 2022). "Through direct competition with SIRPα on the surface of macrophages, E. coli-constructed recombinant hSIRPext binds to CD47 on the surface of leukemia stem cells, which blocks CD47-SIRPα signaling." (PMID 32082311, 2020). "Previously, CD47 on leukemia stem cells was shown to interact with macrophage signal regulatory protein α (SIRPα) and avoid phagocytosis through inducing a “do not eat” signal." (PMID 24019967, 2013).
ovarian carcinoma (17 papers, 2012 to 2026). A malignant neoplasm originating from the surface ovarian epithelium. "Previous research has shown that the oncolytic virus SG635-SF, engineered to encode the SIRPα-IgG1 Fc gene, effectively reduces the viability of the ovarian cancer cell line SK-OV3." (PMID 38970121, 2024). "Compared to control, CD47 blockade therapy with SIRPa-Fc decoy receptor (TTI-621) enhanced macrophage-mediated in-vitro phagocytosis of ovarian cancer cells (BRCA1 mutated, UWB1.289 and its counter cell line with BRCA1 wild type, UWB1.289)." (PMID 37468567, 2023). "Another phase Ib trial is evaluating MIRV alongside SL-172154, a fusion protein consisting of human signal-regulatory protein alpha (SIRPα) and CD40L linked via a human Fc, in patients with platinum-resistant ovarian cancer (NCT05483933)." (PMID 38966169, 2024). "Then we assessed the activity of CD47 blockade therapy with SIRPa-Fc decoy receptor (TTI-621) using intraperitoneal (IP) xenograft ovarian cancer models with three ovarian cancer cell lines (TOV-21G, OVCAR3 and SKOV3)." (PMID 37468567, 2023). "Compared to control, CD47 blockade with SIRPa-Fc decoy receptor (TTI-621) enhanced macrophage-mediated in-vitro phagocytosis of ovarian cancer cells (OVCAR3 and TOV-21G)." (PMID 37468567, 2023). "A preclinical study regarding a novel oncolytic adenovirus carrying a SIRPα–IgG1 Fc fusion gene (termed SG635-SF) showed that SIRPα-Fc fusion protein enhances the anti-tumor effect of oncolytic adenovirus against ovarian cancer." (PMID 36080360, 2022). "A SIRPα‐Fc fusion protein enhances the antitumor effect of oncolytic adenovirus against CD47‐positive ovarian cancer." (PMID 31899582, 2020). "This strategy is being exploited thanks to the antigen CD47, expressed by ovarian cancer cells, that functions as a “don’t eat me signal” through ligation of signal-regulatory protein alpha (SIRPα) expressed on macrophages." (PMID 31096567, 2019). "Potent synergy by blocking CD47/SIRPα and CD24/Siglec-10 pathways, enhances macrophage phagocytosis and anti-tumor immune responses; reduces tumor growth in ovarian cancer models." (PMID 40330466, 2025). "In treating ovarian cancer, the targets for PF-0725787, the dual checkpoint inhibiting BsAb, were CD47/SIRPα and PD-1/PD-L1 in order to maximize anti-tumor immunity." (PMID 38892394, 2024). "Therefore, in this study, we genetically manipulated an oncolytic adenovirus designated SG635‐SF to express an engineered SIRPα and IgG1 Fc fusion protein and investigated its therapeutic effect against CD47‐high‐expressing ovarian cancer cells both in vitro and in vivo." (PMID 31899582, 2020). "ALX‐148 specifically blocks the cd47 receptor, and since CD47/SIRPα axis additionally constrains the efficacy of tumour‐opsonising antibodies, a combination therapy pf ALX‐148 and other anticancer drug could boost their effect in platinum‐resistant ovarian cancer." (PMID 38450975, 2024).